CD4 (CD4 molecule)
Diseases named in the same sentence as CD4 in open-access papers (continued):
Sharing a sentence is not in itself a finding about the gene and the disease.
tumor (continued). "At later time points, the composition of CD4+ TH cells differentiates from a TH1 phenotype to TH17 phenotype, resulting in negative prognostic effects, while the CD8+ TC cells are the key effector cells that control tumor progression." (PMID 30237863, 2018). "CD4+ T cells purified from fresh TUR-B tumour resections did not demonstrate any difference in methylation profile in the IFNG locus compared to PBMCs (p > 0.05)." (PMID 30075815, 2018). "We have shown that potent cytotoxic CD4 T-cells can be induced to citrullinated peptides and these provide efficient tumour therapy in aggressive murine tumour models, with no associated toxicity." (PMID 29570634, 2018). "Notably, CD4+ T cells with B cell-helper features, including high expression of PD-1, ICOS, and CXCL13, are enriched in multiple solid tumors and in murine tumor model, and these cells are preferentially expanded by anti-CTLA4 but not anti-PD-1 therapy." (PMID 30190721, 2018). "In a nutshell, feature (d) quantifies peaks (at the millimeter length scale) of the ratio of the number of non-proliferating CD4 T cells ajdacent to tumor cells over the number of T effector cells adjacent to tumor cells." (PMID 30619761, 2018). "Very consistently, there are elevated anti-tumor molecules such as perforin, granzyme B, CTSE and increased Th1 transcription factor T-bet while decrease of Th1 inhibitory molecule like SOCS1 and Twist1 in the lung of CD4-Chi3l1 KO mice." (PMID 29403003, 2018). "In addition, both CD4+ and CD8+ T cells isolated from the spleens of tumor-bearing mice on day 20 showed evidence of activation and differentiation." (PMID 30298117, 2018). "Even though CD4+ and CD8+ T cells in the tumors express similar and high levels of chemokine receptors important for intestinal migration higher numbers of CD4+ T cells migrate into the tumor." (PMID 29671006, 2018). "We have demonstrated that compared to primary chemoresistant HGSOC, LT survival in HGSOC can be characterized by elevated mutation burden, biallelic inactivation of BRCA1 or BRCA2, and increased CD4+ and CD8+ lymphocytic infiltration in the tumor microenvironment." (PMID 30382883, 2018). "We could demonstrate that OVA expression by the tumor cells, MHC I presentation and recognition of MHC I presented peptide by cocultured CD8+ T cells was mandatory for CD4+ T cell action." (PMID 30214445, 2018). "Elevated CD4+ and CD4+FOXP3+ populations were correlated with shorter recurrence-free survival, and the perivascular CD4+FOXP3+ Treg population in primary tumors was identified as an independent predictor of tumor recurrence in this cohort." (PMID 32914058, 2018). "The lack of MHC class II tumor expression can also be addressed by engineering CD4+ T cells that can recognize HLA-class I-restricted peptides." (PMID 29770138, 2018). "Expression of PD-1 and Tim-3 on tumor-infiltrating CD4+ T cells was not altered by conditional knockout of Eomes in T cells, either." (PMID 30619337, 2018). "The findings thus suggest that 4T1 tumors induce a CD4+ Treg response that is additionally augmented by absence of Shb and that this effect promotes tumor expansion and metastasis." (PMID 29721156, 2018). "Compared with the control, the expressions of CD4, CD8, and IFN-γ were positive in diosgenin-treated cohort, suggesting the infiltration of CD4+ T and CD8+ T cells as well as augmented immune response in tumor tissues." (PMID 30305604, 2018). "In stark contrast to our previous observations with ID8 tumors, B16-F0 (simplified to B16) challenge did not increase the frequency of total γδ T cells or γδ17 T cells in the peritoneal cavity when compared to tumor-free controls, while CD8+ and CD4+ T cells accumulated significantly." (PMID 29750788, 2018). "CD4+ T cells can modulate antitumor immune response in antitumor immunity via activating CD8+ T cells and NK cells; CD8+ T cells impart cytolytic activity on tumor cells." (PMID 30693068, 2018).
tumor (continued). "In CD34+ hHSC-reconstituted, tumor-bearing models, treatment with LY3300054 resulted in an increase of the absolute number of human T cells, an enhanced CD8/CD4 T cell ratio, and increased frequency of PD1+ CD8+ and CD4+ T cells, indicative of T cell activation." (PMID 29712568, 2018). "Positive CK20 expression was related to a higher level of CD4+/PD-1− tumor-infiltrating lymphocytes than negative CK20 expression (73/HPF versus 30/HPF, p < 0.05)." (PMID 30069490, 2018). "Number of CD8+ T cells, but not that of CD4+ T cells, in the tumor formed in Pld2−/− mice was lower than that in the tumor in WT mice, which was confirmed with Pld2−/−/Cas9 mice." (PMID 29674728, 2018). "With regard to the histopathological findings, previous clinical studies have revealed that HF10 increased the number of CD4+, CD8+ and natural killer cells within the tumor, which may lead to the tumor growth reduction and prolonged survival rates." (PMID 29801474, 2018). "Transient CD4+ T cell depletion led to the proliferation of tumor-specific CD8+ T cells in the draining lymph node and increased infiltration of PD-1+CD8+ T cells into the tumor, which resulted in strong anti-tumor effects in tumor-bearing mice." (PMID 30400835, 2018). "The same treatment group had a larger proportion of CD4+ T and CD8+ memory/effector T cells (CD3+CD4+CD44+ and CD3+CD8+CD44+, respectively) among tumor-infiltrating leukocytes, suggesting that the anti–MMP-9/anti-PDL1 combination promotes a functional T cell–mediated antitumor response." (PMID 30500835, 2018). "Likewise, this difference was also observed when we evaluated CD3+, CD4+, and CD8+ T cells in B16F10 and 4T1 LN of tumor-bearing mice." (PMID 30234017, 2018). "Like tumor-specific T cells, male-specific CD4+ T cells in our system encounter antigen in a non-inflammatory context." (PMID 29911570, 2018). "Immune infiltrates were seen at baseline in both subjects, with predominant CD4/8 T-cells in patient #8 with a high PD-1 expression in infiltrating lymphocytes without PD-L1 expression in the tumor environment." (PMID 30400835, 2018). "Based on the flow cytometry analysis that the IFN-γ-secreting cells in GL261 tumors were T cells and CD45hi CD4− CD8− NK subsets, we speculate that T cells and NK cells are the major source of IFN-γ in the tumor microenvironment." (PMID 30333036, 2018). "This suggests that while there is no overall increase in CD4+ infiltration with LB-100/aPD-1 combination, effector CD4+ T cells present in the tumor were nonetheless more functionally active with enhanced IFN-γ production." (PMID 29844427, 2018). "For the verification, whether the increase of circulatory and splenic CD4+/CD8+ T cells influenced their number in the TME, tumor tissues were collected, and total RNA was extracted." (PMID 30079021, 2018). "The level of committed hypomethylated CD4+ T cells were increased in patients with low, non-muscle invasive pT stages as compared to those from patients with muscle invasive pT2 tumours, which was most prominent in Th1 cells." (PMID 30075815, 2018). "We analyzed the immunological components in the tumor microenvironment of STS and found that the components of the antitumor immune response in STS were mainly CD3E/CD4/CD8A-labeled T cells, CD57-labeled NK cells, and CD45RO-labeled memory T cells that can secrete IFN-γ." (PMID 29896199, 2018). "This could be due to the fact that CD4+ TH cells are instrumental to secrete cytokines that modulate CD8+ TC cells and NK cells which in turn control tumor cells." (PMID 30237863, 2018). "An analysis of tumor lesions in wild-type and ST2KO mice revealed that a lack of ST2 was associated with specific and significant reductions in the numbers of CD4+ T cells, CD8+ T cells, dendritic cells, and macrophages." (PMID 30112116, 2018).
tumor (continued). "Cell types expressing PD-1 in the TME include CD8+ T-cells, CD4+ T-cells, Tregs, and CD20+ B-cells, supporting the notion that multiple cell types may potentiate tumor regression following PD-1 blockade." (PMID 30285852, 2018). "Indeed, upon recognition of tumor antigens present in the context of MHC II by macrophages, CD4 T cells secrete IFN-γ that further activates macrophages in the tumor, leading to tumor growth inhibition." (PMID 29780381, 2018). "Subsequently, type II NKT cells were shown to be sufficient for the suppression of tumor immunity in multiple mouse tumor models, in which CD4+CD25+ regulatory T cells (Tregs) do not play a critical role in the regulation of immunosurveillance." (PMID 29520281, 2018). "Growth of subcutaneous CMS5a tumours (1.0–1.2 cm tumour diameter) was significantly attenuated in DUC18 CD8 EV- and BALB CD8 EV-treated groups by i.t. administration compared to BALB CD4 EV (from CD8+ cell-depleted BALB/c splenocytes)-, CMS5a EV- or hPBMC EV-treated groups." (PMID 29382847, 2018). "The gene expression of CD4 and CD8 markers were also evaluated in the tumor tissue." (PMID 30079021, 2018). "Notably, the combinational transplantation of CD4+ and CD8+ iTSCM cells achieved approximately 40% of a complete remission state in tumour-bearing mice." (PMID 28530241, 2017). "Non-cancerous mucosa (14.2 ± 15.1%) and tumor tissue (21.9 ± 12.4%) showed similar percentages of CD4+ T cells in the PD-L1+ fraction." (PMID 28574843, 2017). "Depletion of CD4+ T cells weakly attenuated the anti-tumor effect of alum-CpG-HH2-NY vaccine, supporting that CD4+T cells might be a potent inducer of humoral immunity and required for CD8+ CTL response." (PMID 28515346, 2017). "Analysis of leukocyte tumor content by flow cytometry indicated that anti-PD-1 injection in WT mice induced a small, yet significant, increase in CD45+ and Thy1+ T cells, including both CD8+ and, albeit to a lesser extent, CD4+ TILs." (PMID 29273790, 2017). "Similarly, patients with metastasized colorectal malignancies exhibited significant stimulation of CD3+, CD4+ and CD8+ cells after laser treatment, signifying a tumor-specific cytotoxic T cell activation." (PMID 28393926, 2017). "The percentage of Treg (CD4+/CD25+/FoxP3+) in the tumor was low and irradiation with 2 × 5 Gy induced no higher amounts of Treg when compared to the normal turnover in non-irradiated tumors." (PMID 28337197, 2017). "Although CD4+ T cell depletion did not always result in increased expansion rates of the T cells, the number of tumor-reactive CD8+ T cells was often increased." (PMID 28401257, 2017). "To investigate further a role for CD8+ and CD4+ T cells in mediating anti-tumor responses in WT mice, we treated EMT6 and EMT6siCD200 tumor bearing animals with either an anti-CD8 or anti-CD4 depleting antibody beginning at day 6 post tumor cell injection (x3 injections)." (PMID 28234914, 2017). "A study showed that the CD4+ T cells were significantly increased in tumor, ascites, and peripheral blood of patients with HCC and showed that HBV-specific and HLA class II-restricted CD4+ T cell responses may be related to HBV-related HCC development." (PMID 28761441, 2017). "In contrast, the depletion of CD4 and NK cells did not inhibit the antitumor activity of Vax/aGITR/aPD-1 therapy by day 25 post tumor implantation, indicating these cells played minor roles in the efficacy observed." (PMID 28388572, 2017). "Tumour regression requires the combined absence of all three receptors, is dependent on both CD4 and CD8 T cells and protects the mice from subsequent tumour challenge." (PMID 28300057, 2017). "When inhibiting RANKL-secreting tumor-specific CD4+ T cells, bone metastases but not metastasis to other organs was decreased, indicating a site-specific mechanism." (PMID 29037250, 2017).
tumor (continued). "We report here that antibiotic prophylaxis diminished the endogenous antitumor T cell responses elicited by CTX, impaired the efficacy of ACT using tumor-specific CD4+ T cells, but had no impact on the efficacy of ACT using CD19-CAR T cells." (PMID 29340102, 2017). "However, the response of CD4, CD8, and splenocytes was improved when they were in contact with the triple combination of tumor-derived cells, showing an early and strong induction of cytotoxicity." (PMID 28974950, 2017). "The mutation was found in the CD3dim/CD4+ population, corresponding to tumor T cells, but not in the CD3high/CD4+; CD3high/CD8+ and CD14+ normal cell populations." (PMID 28881727, 2017). "The numbers CD4+ and CD8+ T cells are also critical to anti-tumor immunity." (PMID 28747781, 2017). "Indeed, the number of circulating CD4+ CTL was consistently higher in HCC than in chronic HBV carriers and liver cirrhosis patients, but decreased as tumor progressed." (PMID 28289418, 2017). "Within the tumor microenvironment of Cbx3/HP1γ-insufficient mice or wt mice treated with Cbx3/HP1γ-insufficient CD8+ T cells, we detect an increase of Klrk1/NKG2D+ infiltrating CD8+ effector T cells, a concomitant decrease in CD4+ Treg cells." (PMID 28220815, 2017). "It has also been reported that after undergoing primary tumor excision and/or immunotherapy and presenting a disease-free period, IFNγ-producing type-1 CD4+ T cells prevail in RCC patients, suggesting that tumor environment may promote a type-2 response." (PMID 28409322, 2017). "Interestingly these tumours tend to arise somewhat later than HIV-related BL, in patients with relatively modest reductions in CD4+ T cell counts." (PMID 28893938, 2017). "In general, the immunotherapy does not allow for the complete clearance of the tumor when CD4+ T cells are administered alone." (PMID 29250133, 2017). "Then, we showed that IL-6 secreted by CD4+ T cells can trigger EMT in ccRCC, which may be the source of α-SMA (+) cells, and also enhanced the metastatic ability of tumor cells." (PMID 28846080, 2017). "The tumor immunity and enhanced overall survival induced by inhibin-α vaccination may be passively transferred into naive male BALB/c recipients with either CD4+ T cells, B220+ B cells, or sera from inhibin-α primed mice." (PMID 28428886, 2017). "Activated CD4+T-lymphocytes produce inflammatory cytokines such as, IFN-γ and TNF-α, that can both suppress tumor survival and upregulate the expression of MHC molecules on the surface of tumor cells." (PMID 28220118, 2017). "Subsequent deactivation of Myc in established adenocarcinomas triggers immediate reversal of all stromal changes and tumor regression, which are independent of CD4+CD8+ T cells but substantially dependent on returning NK cells." (PMID 29195074, 2017). "In another study, increased regulatory T cells and tumor-associated macrophages in the tumor microenvironment were also associated with non-responsiveness, while increased GATA3+ and CD4+ T cells were associated with responders." (PMID 28974949, 2017). "Interestingly, microscopic findings showed co‐infiltration of CD4+ and CD8+ lymphocytes in the tumor area in 27 of 36 cases, and CD68+ cells and FoxP3+ cells were diffusely infiltrated in the tumors." (PMID 28602029, 2017). "CD4+CD25+FOXP3+ Treg mediate immunosuppression and play an important role in tumour immune evasion." (PMID 28253320, 2017). "It has been reported that CXCL10 may act in a paracrine fashion affecting the peritumoral CD4+ and CD8+ lymphocytes, and in an autocrine fashion contributing to tumor migration and progression." (PMID 28603578, 2017). "100% of mice that did not receive antibody depletion or mice that received CD4+ T cell or NK cell depletion remained tumor-free for at least 11 weeks after tumor challenge." (PMID 28852471, 2017).
tumor (continued). "Interestingly, while the PD-L1/PD-1 signaling pathway is abundantly engaged in the TME, expression of PD-1 on peripheral CD4+ and CD8+ T cells has been shown to increase with tumor progression." (PMID 28404974, 2017). "We did not observe any significant effect on tumor-infiltrating CD4+FoxP3+ Tregs by any of the treatments compared to the PBS control group." (PMID 28807056, 2017). "A significant delay (P < 0.01) in tumor growth, but not complete tumor regression, was observed following depletion of either CD4 or CD8 T cells." (PMID 28250921, 2017). "Tumour tissues from S21 and S23 samples had high CD8+-T:CD4+-T (TIL) ratios, indicating that these tumours may likely respond to the immune checkpoint blockade therapy." (PMID 28886030, 2017). "In this study we evaluated formally the optimal binding affinity of HLA‐I‐restricted TCRs in CD4+ and CD8+ T cells by using a range of high‐affinity TCRs specific for two well‐studied and therapeutically important HLA A2‐restricted tumour antigens, NY‐ESO‐1157–165 and gp100280–288." (PMID 27324616, 2017). "The TILs could also be detected by flow cytometry in tumor homogenates and the majority of T cells were CD8+ effector memory cells, whereas in peripheral blood the CD4+ cells predominated." (PMID 28955032, 2017). "Boundary conditions We assume that the naive CD4+ T cells and naive CD8+ T cells which migrated from the lymph nodes into the tumor microenvironment have constant densities T^1 and T^8 at the tumor boundary, and that they are activated by IL-12 upon entering the tumor." (PMID 28542574, 2017). "The augmented tumor-specific CTL response observed in mice immunized with NDV infected tumor cells in comparison to mice immunized with non-infected tumor cells was mediated via IFN-α/β and was a result of CD4+ and CD8+ immune T cell cooperation." (PMID 28531117, 2017). "Previous studies have shown that excessive iron can suppress the function of CD4+ T cells, as well as the tumorcidal activity of macrophagocytes and monocytes, but increase the numbers and activities of suppressor CD8+ T cells, impairing anti-tumor responses." (PMID 29069861, 2017). "Moreover, CD3+CD4+ T cells and CD3+CD8+ T cells derived from 4T1-tumor bearing mice expressed higher level of immunosuppressive markers including PD1, PDL1, LAG3, CTLA4 and TIM3 in peripheral blood and spleen than that in normal mice." (PMID 29383101, 2017). "CD4+ or CD8+ T cells were cultured with or without Ly6G+CXCR2− cells sorted from spleen of normal mice or CXCR2+ MDSCs sorted from spleen of 4T1 tumor-bearing mice under the stimulation of anti-CD3 and anti-CD28 for 3 days." (PMID 29383101, 2017). "The immunization with B16-ISAV CBs was not correlated with changes in the CD8 and CD4 populations in the tumor, but it was correlated with an increase of the CD8 and CD4 populations in spleen." (PMID 29062313, 2017). "An increase in non-CAR polyclonal T cells was observed in the tumor environment, which phenotypic analysis indicated to be comprised mostly of immunosuppressive regulatory T cells based on their expression of CD4, CD25, and FoxP3." (PMID 29312333, 2017). "Tumor cells that expressed GFP and immunomodulators were incubated with CD4, CD8, or splenocytes." (PMID 28974950, 2017). "However, not only do immature DCs fail to stimulate naïve T cells to develop into effective CD4+ or CD8+ lymphocytes, but they also activate CD4+ CD25+ regulatory T cells, which enhance the unresponsiveness of effector T cells in the tumor microenvironment." (PMID 28331853, 2017). "The difference may be due to the different viral transgenes and/or different hygiene conditions, since CD4+ T cells from K14‐HPV16 mice showed reactivity to Staphylococcus aureus antigens and induced neutrophil infiltration, resulting in tumor promotion." (PMID 27932444, 2017). "The overall numbers of CD4+ cells in the tumor was not significantly different since there were more memory CD4+ T cells in the CD4-AsiC-PI-treated mouse tumors." (PMID 28290464, 2017).